UCHL5 (ubiquitin C-terminal hydrolase L5)
Description:
Protease that specifically cleaves 'Lys-48'-linked polyubiquitin chains. Deubiquitinating enzyme associated with the 19S regulatory subunit of the 26S proteasome. Putative regulatory component of the INO80 complex; however is inactive in the INO80 complex and is activated by a transient interaction of the INO80 complex with the proteasome via ADRM1.
Synonyms: UCH-L5; UCH37; CGI-70; INO80R
Tractability: Small molecule: it has a binding pocket of medium quality. PROTAC: ubiquitination databases record sites on it; its protein half-life has been measured; a small molecule that binds it is known.
Target class: Cysteine protease CA clan; Cysteine protease; Enzyme; Protease; Cysteine protease C12 family
Gene: Protein-coding gene on chromosome 1 (193,012,246 to 193,060,080, reverse strand). Ensembl gene ENSG00000116750.
Subcellular location: Cytoplasm; Nucleus
Subcellular location (Human Protein Atlas): Cytosol; Nucleoplasm; Nucleoli
Pathways (Reactome):
Metabolism of proteins: UCH proteinases
Signal Transduction: Downregulation of TGF-beta receptor signaling
Gene Ontology:
Molecular function: cysteine-type deubiquitinase activity; endopeptidase inhibitor activity; proteasome binding; protein binding; RNA binding
Biological process: chromatin remodeling; negative regulation of proteasomal ubiquitin-dependent protein catabolic process; positive regulation of DNA-templated transcription; positive regulation of smoothened signaling pathway; protein deubiquitination; regulation of cell cycle; regulation of chromosome organization; regulation of DNA replication; regulation of DNA strand elongation; regulation of proteasomal protein catabolic process; ubiquitin-dependent protein catabolic process
Cellular component: cytosol; Ino80 complex; nucleolus; nucleoplasm; nucleus; cytoplasm
Genetic constraint (gnomAD): Loss-of-function variants: 19 observed, 34.72 expected, observed/expected ratio (o/e) 0.55, 90% interval 0.38 to 0.8. The upper end of that interval is the gene's LOEUF score, 0.8, which puts it in group 3 of 6, group 1 being the genes least tolerant of losing a copy. Missense variants: 218 observed, 302.43 expected, observed/expected ratio (o/e) 0.72, 90% interval 0.64 to 0.81. Synonymous variants: 89 observed, 102.82 expected, observed/expected ratio (o/e) 0.87, 90% interval 0.73 to 1.03.
Homologues: Orthologues: rabbit UCHL5 (99% identical), pig UCHL5 (99% identical), guinea pig UCHL5 (98% identical), mouse Uchl5 (97% identical), chimpanzee UCHL5 (96% identical), dog UCHL5 (95% identical), macaque UCHL5 (94% identical), rat Uchl5 (91% identical), zebrafish uchl5 (89% identical), tropical clawed frog uchl5 (85% identical), Drosophila melanogaster Uch-L5 (60% identical), Drosophila melanogaster Uch-L5R (48% identical), and 1 more. Paralogues in human: BAP1 (44% identical), UCHL3 (20% identical), UCHL1 (16% identical).
Diseases named in the same sentence as UCHL5 in open-access papers:
UCHL5 is named in the same sentence as 54 diseases in open-access papers, as found by Europe PMC text mining. Sharing a sentence is not in itself a finding about the gene and the disease. The quoted sentences say what the papers report.
multiple myeloma (14 papers, 2015 to 2024). "Concurrent pharmacological inhibition of the proteasome-associated DUBs USP14 and UCHL5 reduces proliferation, and increases survival in multiple myeloma xenograft models." (PMID 29474458, 2018). "P5091 (inhibitor of USP7) and b-AP15 (inhibitor of USP14/UCHL5) inhibit the growth of bortezomib-resistant multiple myeloma [41,42,]." (PMID 34272356, 2021). "UCHL5 is a potential marker of gastric cancer and is also involved in the occurrence and development of colon cancer, cervical cancer and multiple myeloma 14-16." (PMID 33046988, 2020). "VLX1570, known as an inhibitor of USP14 and UCHL5, is in the middle of a clinical trial (Phases 1 and 2) to confirm its stability and efficiency for the multiple myeloma (NCT02372240)." (PMID 32486158, 2020). "We next used an siRNA approach to knock down the expression of USP14 and UCHL5 in multiple myeloma (MM) cells." (PMID 27264969, 2016). "Transient knockdown of USP14 or UCHL5 expression by electroporation of siRNA reduced the viability of multiple myeloma cells." (PMID 27264969, 2016). "Moreover, b-AP15, PtPT, and VLX1570, as inhibitors of ubiquitin-specific protease 14 (USP14) and UCHL5, induce apoptosis in myeloma, breast cancer, and prostate cancer cells." (PMID 32596150, 2020). "In 2015, as a competitive inhibitor of proteasomal DUBs (preferring USP14 over UCHL5), VLX1570 became the first case applied in phase I trials for treating multiple myeloma and solid tumors, although it has been discontinued because of dose-limiting toxicity." (PMID 35883466, 2022). "This is achieved by inhibiting the enzymatic activity of USP14 and UCHL5, and VLX1570 shows significant anti‐cancer impact in multiple myeloma and Waldenstrom's macroglobulinemia." (PMID 34854221, 2022). "VLX1570 targets the Ub‐USP14 or Ub‐UCHL5 conjugates and is a reversible non‐selective competitive inhibitor of ubiquitin peptidase 14 (USP14) and ubiquitin carboxyl‐terminal hydrolase 5 (UCHL5) in multiple myeloma." (PMID 34854221, 2022). "VLX1570 is known to induce apoptosis of myeloma by targeting USP4 and UCHL5." (PMID 32486158, 2020). "Although the USP14/UCHL5 DUB inhibitor b-AP15 induced anti-tumor response in several types of malignant tumor including colorectal cancer, myeloma and breast cancer, its effect on human prostate cancer cells, especially the castration-resistant prostate cancers (CRPC), is undefined yet." (PMID 28968984, 2017).
hepatocellular carcinoma (10 papers, 2015 to 2025). A malignant tumor that arises from hepatocytes. "Previously, high UCHL5 expression has been linked to poor prognosis or cancer recurrence in esophageal squamous cell carcinoma, epithelial ovarian cancer, and in hepatocellular carcinoma." (PMID 29474458, 2018). "In summary, our study revealed that UCHL5 is significantly expressed in hepatocellular carcinoma and speeds up tumor growth by encouraging hepatocellular carcinoma cell proliferation and metastasis." (PMID 38773433, 2024). "The findings demonstrated that hepatoma cells expressed more UCHL5 mRNA and protein than normal hepatocytes did and the most significant differential expression of UCHL5 was observed in HepG2 and Hep3B cell lines." (PMID 38773433, 2024). "In esophageal squamous cell carcinoma, hepatocellular carcinoma, and epithelial ovarian cancer, high UCHL5 expression correlated with cancer recurrence and reduced patient survival." (PMID 29474458, 2018). "Overexpression of UCHL5 in hepatocellular carcinoma (HCC) cancerous cells can promote cell migration and invasion through interacting and deubiquitinating PRP19, an essential RNA splicing factor." (PMID 26097878, 2015). "In summary, we have demonstrated for the first time that UCHL5 is a target of HCC and promotes the progression of hepatocellular carcinoma by promoting glycolysis through the activation of the Wnt/β-catenin pathway." (PMID 38773433, 2024). "Ubiquitin C-terminal hydrolase L5 (UCHL5) has been found to aggravate tumor growth and metastasis in several different types of tumor models such as esophageal squamous cell carcinoma, hepatocellular carcinoma, and epithelial ovarian cancer." (PMID 32596150, 2020).
breast carcinoma (9 papers, 2017 to 2025). "Our analysis of several human cancers from the cBioportal database revealed that gene alterations are frequent in UCHL5 including amplification or mutation in several types of human cancer, specifically in 9.8% of breast cancer and 7% of high grade serous ovarian cancer." (PMID 31666925, 2019). "Ubiquitin Carboxyl-terminal Hydrolase 35 (UCH37), encoded by UCHL5, is heavily amplified and is associated with poor outcomes in breast cancer patients." (PMID 41278204, 2025). "Mainly USP4, USP7, USP22, UCHL1, UCHL5, and OTUB1 could be used as biomarkers for each type of cancer such as EOC, breast cancer, melanoma, cervical cancer, and colorectal cancer." (PMID 37107644, 2023).
ovarian carcinoma (9 papers, 2015 to 2024). A malignant neoplasm originating from the surface ovarian epithelium. "Previous studies have demonstrated that the expression level of UCHL5 and associated clinical outcome vary among cancers including gastric, rectal, pancreas, esophageal, hepatocellular, and ovarian cancer." (PMID 31666925, 2019). "Next, we investigated the association between cytoplasmic UCHL5 expression and clinicopathological characteristics in patients with ovarian cancer." (PMID 31666925, 2019). "UCHL5 is up-regulated in most tumor tissues of ovarian cancer patients and is significantly associated with poor prognosis in human epithelial ovarian cancer." (PMID 27604640, 2016). "The high expression of UCHL1 in cervical squamous cell carcinoma, UCHL3 in ovarian cancer, and UCHL5 in lung adenocarcinoma are also used as markers of poor prognosis." (PMID 39034372, 2024). "In line with our previous results in ovarian cancer cell lines, the addition of bAP15 inhibited UCHL5 and reduced cell invasiveness, as determined by Matrigel cell invasion experiments." (PMID 37762005, 2023). "As activated TGF-β signaling is involved in ovarian cancer progression, these findings suggest that UCHL5 inhibition offers potential opportunities for a novel targeted therapy against TGF-β-activated ovarian cancer." (PMID 31666925, 2019). "Expression of UCHL5 was found in the majority of nuclei whereas its expression in the cytoplasm was various in ovarian cancer tissue." (PMID 31666925, 2019). "Here, we found that aberrant UCHL5 expression predicted shorter progression-free survival (PFS) in a cohort of 1435 patients with ovarian cancer described in the Gene Expression Omnibus and The Cancer Genome Atlas databases." (PMID 31666925, 2019). "The ubiquitin carboxyl terminal hydrolases UCH37 (also known as UCHL5) and UCHL1 have both been implicated in ovarian cancer." (PMID 25605410, 2015). "We also analyzed a database of gene expression and survival of 1435 patients with ovarian cancer, downloaded from Gene Expression Omnibus and The Cancer Genome Atlas (Affymetrix HG-U133A, HG-U133A 2.0, and HG-U133 Plus 2.0 microarrays) for UCHL5 mRNA expression, and generated survival curves." (PMID 31666925, 2019). "Our data revealed that cytoplasmic UCHL5 was upregulated in ovarian cancer, suggesting that cytoplasmic UCHL5 may serve as a marker of ovarian cancer progression." (PMID 31666925, 2019). "Furthermore, we found that cytoplasmic expression of UCHL5 is significantly correlated with its regulation of ovarian cancer." (PMID 31666925, 2019). "However, the role of UCHL5 in the regulation of TGF-β signaling in ovarian cancer pathogenesis is still unclear." (PMID 31666925, 2019). "Our results suggested that UCHL5 activity is upregulated at a certain frequency in ovarian cancer." (PMID 31666925, 2019).
ovarian carcinoma (continued). "Moreover, the statistical analysis of the clinicopathological factors showed that the differentiation of ovarian cancer, FIGO stage, lymph node metastasis, and peritoneal dissemination were significantly associated with the expression level of cytoplasmic UCHL5." (PMID 31666925, 2019). "Ongoing in vivo pre-clinical work will help elucidate the various contributions of UCHL5 toward TGF-β signaling, clarifying the ultimate outcome and potential benefits of inhibition of UCHL5 in patients with ovarian cancer." (PMID 31666925, 2019). "bAP15, an inhibitor of the 19S proteasome DUBs UCHL5 and USP14, results in cell growth inhibition in several human cancers; however, the mechanism remains poorly understood in ovarian cancer." (PMID 31666925, 2019). "In the present study, we confirmed that the blockade of UCHL5 activity by the DUB inhibitor bAP15 inhibited expression of phospho-Smad2/Smad3 in a concentration-dependent manner and induced apoptosis in ovarian cancer cells." (PMID 31666925, 2019). "Therefore, we further hypothesized that the levels of UCHL5, as a potential DUB to regulate TGF-β signaling, may correlate with clinical outcome in ovarian cancer." (PMID 31666925, 2019). "To date, no data has been available regarding the prognostic role of UCHL5 in ovarian cancer." (PMID 31666925, 2019).
endometrial cancer (6 papers, 2020 to 2024). Primary or metastatic malignant neoplasm involving the endometrium (mucous membrane that lines the endometrial cavity). "The presence of UCHL5 up regulates and activates β-catenin, thereby promoting the proliferation of endometrial cancer." (PMID 38773433, 2024). "Meanwhile, it has been suggested that UCHL5 promotes the proliferation of endometrial cancer by activating Wnt/β-catenin signaling." (PMID 39068672, 2024). "In another recent study using endometrial cancer cells, UCHL5 reportedly promotes cancer growth by positively regulating the Wnt signaling pathway." (PMID 35256667, 2022). "Expanding the expression levels of UCHL5 has been demonstrated to accelerate the growth of endometrial cancer." (PMID 36428630, 2022). "Since the expression of UCHL5 was highest in HCE-1-A endometrial cancer cells, we knocked down UCHL5 expression using lentiviral-mediated shRNA in HCE-1-A cells to demonstrate the actions of UCHL5 on tumorigenesis." (PMID 32596150, 2020). "Since the expression of UCHL5 was relatively lower in AN3-CA endometrial cancer cells, we increased the expression of UCHL5 by lentiviral infection in AN3-CA cells." (PMID 32596150, 2020). "This regulatory relationship between UCHL5 and β-catenin also exists in endometrial cancer." (PMID 38773433, 2024). "In addition, UCHL5 overexpression mediated by lentivirus vectors activated Wnt/β-catenin signaling in endometrial cancer cells and resulted in a decrease in apoptosis and an increase in proliferation." (PMID 32596150, 2020).
esophageal squamous cell carcinoma (6 papers, 2014 to 2022). Esophageal squamous cell carcinoma (ESCC) is a type of esophageal carcinoma (EC) that can affect any part of the esophagus, but is usually located in the upper or middle third. "UCHL5 can be a predictor of poor survival in esophageal squamous cell carcinoma (ESCC) after curative resection." (PMID 33046988, 2020). "However, similar to DRAIC, UCHL5 has been corroborated to play conflicting biological effects in cancers: The superior expression of UCHL5 was observed in esophageal squamous cell carcinoma tissues, and was correlated with TNM stage, lymph node metastasis, recurrence rate and poor prognosis." (PMID 32351584, 2020). "UCHL5 is abnormally elevated in human cancer tissues or cell lines, including cervical carcinoma, epithelial ovarian cancer (EOC), esophageal squamous cell carcinoma (ESCC), lung cancer, and pancreatic carcinoma." (PMID 36428630, 2022). "Recently several DUBs have been shown to be involved in cancer progression, for example UCHL5 is up-regulated in human cancer including cervical carcinoma and esophageal squamous cell carcinoma (ESCC), and its expression has been identified as a poor prognostic indicator for ESCC as well." (PMID 24465953, 2014).
gastric cancer (6 papers, 2018 to 2024). A primary or metastatic malignant neoplasm involving the stomach. "Here, we demonstrate, to our knowledge for the first time, that in certain subgroups of gastric cancer patients, UCHL5 immunoexpression in tumor tissue is linked to increased survival." (PMID 29474458, 2018). "Association of UCHL5 with clinicopathological variables in gastric cancer patients." (PMID 29474458, 2018). "Interestingly, patients with high UCHL5 expression have better prognosis in later stages of both pancreatic and rectal cancer, whereas a similar survival benefit was linked to lower stages (stages I-II) of gastric cancer." (PMID 29474458, 2018). "For example, it was found in gastric cancer cells that DRAIC can promote the degradation of NFRKB and inhibit the proliferation and metastasis of gastric cancer cells by blocking NFRKB de-ubiquitination mediated by UCHL5." (PMID 34306024, 2021). "The 5-year cancer-specific survival (CSS) of stages I-II gastric cancer was 77.2% (95% CI 69.2–83.4) in patients with positive UCHL5 immunoexpression, compared to 59.0% (95% CI 41.3–73.0) in patients with negative UCHL5 immunoexpression." (PMID 29474458, 2018). "Most gastric cancer samples, according to the Human Protein Atlas, display predominantly moderate to low UCHL5 immunoreactivity." (PMID 29474458, 2018). "Contrary to these findings, we here demonstrate that positive UCHL5 immunoexpression is a predictor for better survival in certain subgroups of gastric cancer patients." (PMID 29474458, 2018). "UCHL5 expression in gastric cancer correlates with a better prognosis." (PMID 39605891, 2024). "Here, we have assessed by immunohistochemistry UCHL5 tumor expression in gastric cancer." (PMID 29474458, 2018). "UCHL5 is thus a potential marker in gastric cancer with new prognostic relevance." (PMID 29474458, 2018). "Here, we have investigated the potential prognostic role of UCHL5 in gastric cancer." (PMID 29474458, 2018). "lncRNA DRAIC also hindered cell metastasis through its interaction with UCHL5 and repression of NFRKB deubiquitination in gastric cancer." (PMID 35992823, 2022). "In gastric cancer, lncRNA DRAIC has also been indicated to inhibit the proliferation of SGC-7901, HGC-27, and MKN45 cells by binding to UCHL5 and accelerating the ubiquitination of NFRKB." (PMID 35992823, 2022).